ENSG00000199470
Synonyms: LOC124900237
Gene: Small nucleolar RNA gene on chromosome 7 (12,700,758 to 12,700,889, reverse strand). Ensembl gene ENSG00000199470.
Gene Ontology:
Biological process: RNA processing
Cellular component: nucleolus
Homologues: Orthologues: rat LOC120102004 (64% identical). Paralogues in human: SNORA64 (80% identical), SNORA10 (55% identical), SNORA10B (55% identical).